MIR612 (microRNA 612)
Synonyms: hsa-mir-612; MIRN612
Gene: MicroRNA gene on chromosome 11 (65,444,458 to 65,444,557, forward strand). Ensembl gene ENSG00000283791.
Gene Ontology:
Biological process: miRNA-mediated post-transcriptional gene silencing
Cellular component: RISC complex
Homologues: Orthologues: chimpanzee ptr-mir-612 (100% identical).
Diseases named in the same sentence as MIR612 in open-access papers:
MIR612 is named in the same sentence as 1 disease in open-access papers, as found by Europe PMC text mining. Sharing a sentence is not in itself a finding about the gene and the disease. The quoted sentences say what the papers report.
vitiligo (1 paper, 2020). Generalized well circumscribed patches of leukoderma that are generally distributed over symmetric body locations and is due to autoimmune destruction of melanocytes. "MS and vitiligo shared 37 differentially expressed (positive co-expressed) genes, all of which showed contradictory expressions exceptSPEN,NEAT1,MIR612,MALT1 andKMT2A (similar expression)." (PMID 33763205, 2020).